PRLR (prolactin receptor)
Diseases named in the same sentence as PRLR in open-access papers (continued):
Sharing a sentence is not in itself a finding about the gene and the disease.
breast cancer (continued). "In addition, autocrine/paracrine prolactin appears to be a survival factor in this subpopulation of breast cancer cells and is induced by treatment with doxorubicin or paclitaxel, as treatment with the PRLR antagonist Δ1–9 potentiates the efficacy of such drugs." (PMID 18681966, 2008). "The strongest associations between individual SNPs and breast cancer risk were with SNP34 (rs9466314) in "block 2" of PRL (co-dominant effect OR, 1.48; 95% CI, 1.00–2.18; p = 0.049) and SNP49 (rs34024951) in block 3 of PRLR (co-dominant effect OR, 0.85; 95% CI, 0.73–0.99; p = 0.032)." (PMID 18053149, 2007). "Controversially, while PRL overexpression in cell culture enhances tumor growth, PRLR knockdown or antagonism can lead to more aggressive but less differentiated tumors, highlighting the context-dependent nature of PRL's role in breast cancer." (PMID 41370498, 2025). "To build upon these results and examine its validity in human breast cancer tumor samples, we investigated PRLR and CCN2 gene expression profiles in the breast cancer SCAN-B (n = 3207) and METABRIC (n = 1992) cohorts." (PMID 40157909, 2025). "This analysis revealed a positive correlation between PRLR and the YAP suppressor Hippo pathway and a co-expression gene network driving favourable patients’ survival outcomes in breast cancer." (PMID 40157909, 2025). "Having demonstrated a molecular antagonism between PRL/PRLR pathway and YAP-CCN2 pathway in mammary and breast cancer cells, we next sought to determine the clinical impact of this antagonism regarding breast cancer prognosis and potential therapeutic value." (PMID 40157909, 2025). "Altogether, based on our bioinformatics analysis and functional validation experiments these results established a link between PRL/PRLR and Hippo pathway and as an important negative regulator of YAP-CCN2 pathway in breast cancer." (PMID 40157909, 2025). "While PRL has been shown to regulate Hippo pathway leading to pigeon crop epithelial cell proliferation, our study showed that PRL/PRLR/Jak2 pathway results in Hippo pathway activation and nuclear exclusion of YAP in mammary epithelial and breast cancer cells." (PMID 40157909, 2025). "Besides, activation of PRLR pathway by PRL could desensitize breast cancer cells to tamoxifen." (PMID 38898487, 2024). "Conversely, among postmenopausal women, prolactin was similarly associated with breast cancer risk regardless of pSTAT5 expression or expression of PRLR or pJAK2, suggesting that this pathway may not be the sole or even primary mechanism of action in this population." (PMID 36882838, 2023). "In the case of luminal breast cancer, two meaningful activators have been described: IL-6 receptor (IL-6R) and PRL receptor (PRLR)." (PMID 37834225, 2023). "In cell line-based assay involving breast cancer cells (MCF-7 and T47D), it has been found that the PRL/PRLR triggers EGFR2 phosphorylation (tyr1221 and 1222) via JAK2, activating the downstream PI3K/AKT signaling." (PMID 37415164, 2023). "The breast cancer cell line, MCF-7, which is known to express GHR and PRLR mRNA (Cancer Cell Line Encyclopedia) was used as a positive control." (PMID 37043098, 2023). "Estradiol induces transcriptional activation/expression of the PRLR gene, and subsequent studies revealed the essential role of autocrine PRL released by breast cancer cells and CDK7 in estradiol-induced PRLR promoter activation and upregulation." (PMID 36187116, 2022). "In a different approach, Ali and her colleagues used CRISPR/Cas9 to reduce PRLR expression in the ER+ MCF7 and HER2+ SKBR3 breast cancer cell lines." (PMID 35784527, 2022). "Altogether, these results implicate that loss of PRL/PRLR expression contributes to the initiation and progression of breast cancer and argues against a role for PRL/PRLR in promoting breast tumorigenesis." (PMID 36157462, 2022). "In premenopausal women with breast cancer, there are higher-than-average levels of serum PRL together with elevated PRLR expression." (PMID 36187116, 2022).
breast cancer (continued). "A study using G129R (PRLR antagonist) and trastuzumab (monoclonal antibody targeting HER2) as a combination therapy to inhibit HER2+ breast cancer cells and a nude mouse xenograft model showed inhibition of cell proliferation." (PMID 36187116, 2022). "A strong correlation between breast cancer with increased PRL and PRLR has been reported in several studies." (PMID 36187116, 2022). "A preclinical study of the anti-PRLR antibody REGN2878-DM1 suggested induction of cell-cycle arrest and apoptosis in PRLR expressing breast cancer cell lines, and also exhibited synergistic activity with fulvestrant." (PMID 36714582, 2022). "In this review, we examine the role of crosstalk between PRLR and ERBB1/2 signaling pathways in the activation of unliganded ERα, cyclin-D1 and other oncogenic factors (MYC, FOS, JUN) in breast cancer." (PMID 34572912, 2021). "In a recent study performed in patient breast tumor samples, co-expression of PRLR with TGFbR was observed in HER2 overexpressed (HER2+) and luminal breast cancer molecular subtype." (PMID 34572912, 2021). "While PRL tends to be elevated in the serum of breast cancer patients, breast cancer cells also synthesize PRL locally as an autocrine/paracrine growth factor and overexpress PRLR to utilize PRL to promote their growth." (PMID 34077462, 2021). "In this review we highlight the crosstalk between downstream signaling cascades activated by PRLR and EGFR/HER2 in breast cancer and discuss how these receptors work together to affect breast cancer behavior and promote cancer progression." (PMID 34572912, 2021). "Higher expression levels of PRLR were found in HER-2, luminal A and luminal B breast cancer subtypes." (PMID 34572912, 2021). "The produced anti-HER2/PRLR bsADC not only boosts trafficking of HER2, but also displays greater activity than single HER2 ADC or PRLR ADC in breast cancer cells with intermediate HER2 and low PRLR levels." (PMID 34696218, 2021). "Both compounds bound to the extracellular domain (ECD) of the PRL receptor (PRLR) at 1–3 micromolar affinity and abrogated PRL-induced breast cancer cell (BCC) invasion and malignant lymphocyte proliferation." (PMID 34071395, 2021). "In this review, we have provided ample evidence to support the significant role for PRLR and EGFR/HER2 signaling crosstalk in breast cancer." (PMID 34572912, 2021). "Contrary to the believed role of PRLR in breast cancer progression, recent studies have indicated that PRL exerts anti-tumorigenic effects in HER2 positive breast cancer cells through regulation of stemness." (PMID 34572912, 2021). "Prolactin receptor (PRLR) and growth hormone receptor (GHR) are closely related to the occurrence and development of breast cancer, and breast cancer cell endogenously express GHR, PRLR and GHR-PRLR heterodimer." (PMID 33362552, 2020). "PRLR was among the top-100 genes positively correlated with FASN gene expression (r = 0.31, p < 0.0001) in the METABRIC breast cancer dataset." (PMID 33335078, 2020). "Several studies suggest that there is potential cooperation between PRLR and HER2 during breast cancer progression." (PMID 33335078, 2020). "Studies have shown that the occurrence and development of breast cancer are closely related to GH/PRL, and PRLR and GHR are co-expressed on breast cancer." (PMID 33362552, 2020). "Next we investigated the mechanism of killing of breast cancer cells mediated by the bispecific antibody PRLR-DbsAb targeting CD3 and PRLR." (PMID 32398042, 2020). "Studies have indicated that PRLR and GHR are closely related to the occurrence and development of breast cancer, and breast cancer cell endogenously express GHR, PRLR." (PMID 33362552, 2020). "To distinguish the impacts of matrix stiffness and ligand density on PRL signals in breast cancer cells, we examined PRL-induced signaling in ERα+, PRLR+ breast cancer cell lines cultured on well-characterized polyacrylamide hydrogels coated with collagen-I." (PMID 27344177, 2016).
breast cancer (continued). "Using tissue microarrays and gene profiling databases of breast cancer patients, our results identified a novel and relevant subgroup within TNBC characterized by PRLR expression and luminal-epithelial characteristics." (PMID 27480353, 2016). "In these studies we also found ERBB2/HER2, a member of epidermal growth factor receptor family which is overexpressed in about 10% of the ER+ breast cancers phosphorylated and activated by JAK2 induced by PRL through PRLR." (PMID 27564112, 2016). "Herein, the ESR1, PGR, PRLR and GHR gene expression were analyzed and the results showed all hormone receptors to be significantly lower expressed in malignant mammary tumors compared to the group of reference tissue and benign tumors." (PMID 27649560, 2016). "Prolactin receptor (PRLR) and epidermal growth factor receptor (EGFR/ERBB1) have important roles in the physiology of the human breast and in the etiology and progression of breast cancer." (PMID 27564112, 2016). "Data from human breast cancer cell lines, patient tumor samples and clinical studies indicate that P/PR and PRL/PRLR signaling pathways contribute to early stage human breast cancer progression." (PMID 27248476, 2016). "Gene expression of ERα (ESR1), PGR, PRLR, GHR and CDH-1 was detected in normal mammary tissues and in all mammary neoplasms, except in one carcinoma." (PMID 26370564, 2015). "Recent studies have begun to link genetic variations in the genes for PRL and the prolactin receptor (PRLR) and breast cancer." (PMID 21276249, 2011). "Additionally, we examined the association between PRL and PRLR SNPs and serum prolactin levels among controls, hypothesizing that altered serum prolactin levels may be an intermediate marker between genetic variation in PRL and PRLR and breast cancer risk." (PMID 21470416, 2011). "Our data did not support the hypothesis that serum prolactin levels differ for women with PRL and PRLR genotypes associated with breast cancer; prolactin levels did not vary by genotype for any of the breast cancer-associated SNPs in this study (rs13436213, rs249537, and rs7718468)." (PMID 21470416, 2011). "The ER+ breast cancer cell lines T47D, MCF7, the ER- MDA-231, BT-474 and the non-tumorigenic epithelial cell line MCF10A were chosen for varying levels of PRLr expression (relative PRLr expression: T47D>MCF7>BT-474≈ MDA-231≈ MCF10A)." (PMID 18254957, 2008). "We investigated a possible relation between prolactin receptor (PRL-R) or IL-2 receptor alpha (IL-2Rα, CD25) expression on circulating T lymphocytes and their apoptosis in patients with breast cancer." (PMID 12698200, 2003). "Indeed, efforts have been directed to block PRL as a therapeutic avenue in breast cancer, including the generation of PRL antagonists (Del1-9-G129R-hPRL, G129R-Prl) and PRLR antagonist (LFA102)." (PMID 40157909, 2025). "The regulons SPIB, STAT4, and ZMYND8 were seen as the master regulators of immune modulation in PRLR-low patients who did not experience early breast cancer events." (PMID 40723262, 2025). "Thus, promoting PRL/PRLR pathway and/or blocking YAP-CCN2 can be exploited as differentiation therapeutic targets in breast cancer." (PMID 40157909, 2025). "Similarly, in breast cancer, PRL/PRLR signaling has been shown to suppress breast cancer stem cell populations." (PMID 40157909, 2025). "Similarly, some researchers also reported the role of PRLR in the etiology and proliferation of prolactin (PRL)-induced breast cancer (Kavarthapu, Anbazhagan & Dufau, 2021)." (PMID 39253602, 2024). "Immunotoxin targeting PRLR (N8-PE24) was constructed with splicing-intein technique, and the efficacy of N8-PE24 against breast cancer was evaluated using in vitro and in vivo methods, including analysis of cells growth or apoptosis, 3D spheroids culture, and animal xenografts." (PMID 38898487, 2024). "In breast cancer, both PRL and PRLR are extensively expressed." (PMID 37834225, 2023).
breast cancer (continued). "The role of PRL and PRL receptors (PRLR) in tumor progression and tumorigenesis is well known, and several studies have manifested the regulatory involvement of PRLR in medication responsiveness and the prometastatic effect of PRL on breast cancer and other gynecological cancers." (PMID 37168445, 2023). "Resembling canine mammary tumors, PRL is largely not expressed while PRLR is expressed in human breast cancers." (PMID 37789381, 2023). "Similarly, direct knock out of the PRLR in ER+ and HER2-E breast cancer cell lines led to enhanced tumorigenic and metastatic phenotype as well as resistance to conventional therapies." (PMID 36157462, 2022). "In addition, gene expression level of PRLR was also evaluated in relation to intrinsic molecular subtypes, tumor grade, and patient outcome using GOBO database for 1881 breast cancer patients." (PMID 36157462, 2022). "Given these variables, it is not surprising that the proportion of PRLR-expressing breast cancers varied from 25-83%." (PMID 35784527, 2022). "Interestingly, we have previously found that there is positive correlation of expression between PRLR and FOXA1 in breast cancer cases." (PMID 36157462, 2022). "This led the authors to conclude that PRLR is generally not strongly upregulated in human breast cancer." (PMID 36157462, 2022). "However, multiple recent studies have reported PRLR protein expression in ER+, HER2+ and triple negative (TNBC) breast cancers, in sharp contrast to the epidemiologic link between PRL and development of only ER+ breast cancers." (PMID 35784527, 2022). "Although PRLR is highly expressed by many tumors across breast cancer subtypes, data from small clinical trials inhibiting PRL action are difficult to interpret, and studies of xenografts, particularly of breast cancer cell lines, are conflicting." (PMID 35784527, 2022). "Lastly, when PRLR-DbsAb was delivered in combination with a PD-1 antibody, anti-tumor activity was enhanced against MDA-MB-231 cells supporting the rationale of targeting PRLR with the novel BsAbs technology for PRLR-expressing breast cancers." (PMID 36714582, 2022). "The lack of anti-tumorigenic effects of blockers of PRLR suggests that the described pro-tumorigenic role of PRL in breast cancer BC is not of clinical value." (PMID 36157462, 2022). "G129R as an antagonist has the great potential to target the PRL/PRLR pathway since its binding to PRLR does not promote growth of breast cancer cells, instead, induces autophagy-related cell death." (PMID 34077462, 2021). "Prolactin through PRLR can activate both EGFR and HER2 downstream signaling pathways which in turn leads to activation of other oncogenic growth factors that promote growth, survival, and proliferation of breast cancer cells." (PMID 34572912, 2021). "Prolactin receptor (PRLR) and epidermal growth factor receptor (EGFR/ERBB) signaling pathways activated by prolactin (PRL) and epidermal growth factor (EGF), have a major role in the mammary gland development and in the etiology of breast cancer, respectively." (PMID 34572912, 2021). "Multiple evidence has shown crosstalk between PRLR and EGFR signaling pathways in breast cancer." (PMID 34572912, 2021). "We demonstrated that the MICA-G129R fusion protein not only binds to human natural killer NK-92 cells and PRLR-positive human breast cancer T-47D cells, but also promotes NK cells to release granzyme B and IFN-γ and enhances the cytotoxicity of NK cells specifically on PRLR-positive cells." (PMID 34077462, 2021). "This approach ensured that all potential inhibitors of the PRL signaling cascade were identified, and that ‘hits’ recognized by the more sensitive, non-human lymphocytes also blocked PRL signaling in PRLR-expressing breast cancer cells." (PMID 34071395, 2021).
breast cancer (continued). "In xenograft models with breast cancer cell line T47D, NOD/SCID mice intraperitoneally injected with PRLR-DbsAb exhibited significant inhibition of tumor growth and a longer survival compared to mice treated with PRLR monoclonal antibody (PRLR mAb)." (PMID 32398042, 2020). "In addition, using large cohorts of human breast cancer cases, PRL receptor (PRLR) expression was found to be downregulated during tumor progression, from benign, in situ to invasive carcinoma." (PMID 30987013, 2019). "PRLR and EGFR both have important roles in human breast cancer." (PMID 27564112, 2016). "Indeed, we have previously shown that PRL, through PRLR/Jak2 signaling suppresses epithelial-mesenchymal-transition (EMT) and reduces the invasive properties of breast cancer cells." (PMID 27480353, 2016). "Previous evidence indicates that breast cancer cell motility is related to the abundance of PRL and PRLR transcripts, therefore suggesting the hypothesis that PRL signaling may have a role in this phenomenon." (PMID 26733941, 2015). "The STAT5 pathway has been shown to mediate PRLR activity and regulate mammary gland development, differentiation, and proliferation, whereas EGFR is a central growth factor pathway in mammary gland development and a subset of breast cancers." (PMID 23938070, 2013). "Currently, not much data is available about prolactin receptor (PRLR) expression in canine mammary tumors." (PMID 22647582, 2012). "Expression of PRLR protein was demonstrated in canine mammary tumors and in non-neoplastic canine mammary tissues using a polyclonal goat anti human PRLR antibody (R&D Systems, USA)." (PMID 22647582, 2012). "In contrast to its lack of effect in monolayer culture, PRLR antagonism with Δ1–9 profoundly inhibits colony formation of both breast cancer cell lines and primary tumour samples." (PMID 18681966, 2008). "As PRLR and growth hormone receptor (GHR) are closely involved in the incidence and development of breast cancer which typically express PRLR, GHR, and GHR-PRLR heterodimers, the use of a combination PRLR and GHR antagonists may be a better strategy for breast cancer treatment." (PMID 36714582, 2022). "Although PRL/PRLR inhibitors have not shown robust promise as monotherapies, there has been long term interest in their interaction with other treatment modalities, especially with anti-estrogens in ER+ breast cancers." (PMID 35784527, 2022). "In contrast, an antibody drug conjugate (ADCs) targeting PRLR may provide superior therapeutic outcomes including and extending beyond estradiol-insensitive breast cancer populations since its mechanism of action is not dependent on hormonal dependency." (PMID 34107902, 2021). "In breast cancer, PRLR expression is independent of estrogen receptor (ER) expression." (PMID 34071395, 2021). "Recently, scientists have focused on the role of the prolactin receptors (PRL-R) and serum prolactin (PRL) in the carcinogenesis, prognosis, and metastasis of breast cancer (BC)." (PMID 34945164, 2021). "PRLR could be another promising antigen to be targeted in breast cancers, especially the ones lacking effective targets, like triple negative cancers." (PMID 34077462, 2021). "There is no study on the expression of PRLR in breast cancer tissues in china." (PMID 32398042, 2020). "This latter role is supported by the association between prolactin/PRLR down-regulation and significantly better survival outcome in patients with breast cancer, which is consistent with the lack of anti-tumorigenic effects and therapeutic benefits observed in clinical trials with PRLR antagonists." (PMID 33335078, 2020). "For a better evaluation of this point, the correlation of the co-expression of PRLR and TGFβ receptors in relation to tumor grade was investigated using the Gene expression-based Outcome for Breast cancer Online (GOBO) database, a large publicly available database of 1881 breast cancer cases." (PMID 30987013, 2019).